CCR1 (C-C motif chemokine receptor 1)
Diseases named in the same sentence as CCR1 in open-access papers (continued):
Sharing a sentence is not in itself a finding about the gene and the disease.
tumor (continued). "This activity occurs through C-C motif chemokine ligand 15 and C-C motif chemokine receptor 1 (CCL15-CCR1), promoting tumor growth and cell progression." (PMID 34769401, 2021). "CCR5 and CCR1 are expressed by multiple myeloma (MM) cells and their engagement induces tumor cell survival, migration and homing to the bone marrow." (PMID 32630699, 2020). "Other chemokines and their receptors with a central role in MSC tumor homing are C-C motif chemokine receptor 1 (CCR1), CCR7, CCR9, C-X3-C motif chemokine ligand 1 (CX3CL1), CXCR5, and CXCR6." (PMID 33117154, 2020). "They noted that mice with CCR1 cell depletion showed a reduction in tumor growth and liver metastases, with respect to CRC mouse models with wild-type BM." (PMID 32722068, 2020). "The data generated in the ID8 tumor model suggests that deletion of CCR1 expression resulted in extended survival in vivo." (PMID 32963283, 2020). "In radiofrequency ablation-treated tumors of CCR1 deficient mice the loss of CCR1 affects the accumulation of CD11C+, CD4+, and CD8+ T cells in the tumor." (PMID 31311583, 2019). "CXCR4, cooperate with chemokine receptor (CCR1 and/or CCR2) to promote metastasis-associated macrophage (MAM) accumulation and thereby metastatic tumor growth." (PMID 30190788, 2018). "In aggressive malignancies, metastatic MAMs arrive at secondary sites and in turn recruit inflammatory CCR2 bearing monocytes by CCL2, which in themselves release CCL3 and express CCR1, amplifying tumor potential." (PMID 28441391, 2017). "CCR1-/- mice treated with 4NQO presented a similar production of tumours and histopathological score in comparison with the WT mice." (PMID 28881626, 2017). "In the context of OSCC, one study previously showed the expression of CCL3 and CCR1 in tumour samples and metastatic lymph nodes and correlated it with poor cumulative survival." (PMID 28881626, 2017). "CCR1 (CD191), a chemokine receptor, is expressed by several types of white blood cells, lymphocytes, astrocytes, neuron, and tumor cells." (PMID 28389653, 2017). "Upon ligand binding, CCR1 directly or indirectly stimulates tumor growth, cell adhesion, and cytokine secretion." (PMID 28389653, 2017). "A recent report also shows that another CCR1 antagonist (CCX721) reduces tumor burden and osteolysis in a mouse model of multiple myeloma bone disease." (PMID 26275794, 2015). "Loss of CCR1 also prevents MAM-cancer cell interactions and following retention of MAMs in the tumor-challenged lung." (PMID 26275794, 2015). "First of all, the effect of CCL8 on dermal fibroblasts, melanocytes and CCR1-expressing tumor cell lines was examined, using MTT-test." (PMID 26320180, 2015). "Unexpectedly, stroma IMCs are found to play a pro-tumourigenic role in vivo since the suppression of IMC recruitment through CCR1 inhibition profoundly decreases tumour burden." (PMID 26183450, 2015). "NK cells migrate to lymph nodes mainly by utilizing CXCR3, while their migration to the inflamed tissues including tumor sites involves CCR1, CCR2, CCR5, CXCR3, and CX3CR1." (PMID 24966464, 2014). "The CCR1+ myeloid cells appeared to enhance tumor invasion by producing metalloproteinases MMP9 and MMP2." (PMID 25326065, 2014). "Actually, numerous chemoattractant GPCRs, such as CCR1, CCR5, CXCR5, CXCR7, and PAFR, are expressed by various types of tumor cells and are implicated in tumor growth." (PMID 25110692, 2014). "The critical role of CCR1 in tumor progression was confirmed in the MDR2 knockout model, in which mice deficient for CCR1 and MDR2 had smaller tumors than MDR2 knockout mice." (PMID 24646914, 2014). "There was increased expression of CXCR2, CXCR3, and CCR1 in the tumour islets of ES compared with poor survival (PS) patients (p = 0.007, 0.01, and 0.002, respectively)." (PMID 20429924, 2010).
tumor (continued). "There was significantly increased expression of CXCR2, CXCR3, and CCR1 in the tumour islets of ES compared with PS patients [median 6.5 versus 2.6, (p = 0.007), 12.7 versus 3.2, (p = 0.01), and 24.3 versus 2.4 cells/mm2, (p = 0.002), respectively]." (PMID 20429924, 2010). "There was an association between 5 year survival and tumour islet CXCR2, CXCR3 and CCR1 density (p = 0.02, 0.003 and <0.001, respectively) as well as stromal CXCR3 density (p = 0.003)." (PMID 20429924, 2010). "If true, we would expect that patients with improved survival would have high tumour islet expression of chemokine receptors known to be associated with favourable prognosis in cancer such as CXCR3 and CCR1." (PMID 20429924, 2010). "We used immunohistochemistry to identify cells expressing CXCR1, CXCR2, CXCR3, CXCR4, CXCR5 and CCR1 in the tumour islets and stroma in 20 patients with surgically resected NSCLC." (PMID 20429924, 2010). "Expression of CCR1 was found in all tumor samples predominantly on polynucleated giant cells of benign origin, but also on a small number of tumor cells." (PMID 18215331, 2008). "While diverse mononuclear cells express CCR1, its expression has also been described on tumor cells." (PMID 18215331, 2008). "For these four patients, our molecular analyses suggested an initial significant chemoresistance of the localised tumour cell population, even though one patient was classified as GR in CCR1." (PMID 12799638, 2003). "Although previous studies on the CCL15-CCR1 axis have predominantly focused on tumor-derived CCL15 recruiting CCR1+ immune cells, our findings revealed that CCR1 is expressed at significantly higher basal levels in ESCC cells compared to normal esophageal epithelial HET-1A cells." (PMID 40740234, 2025). "Similarly, CCL15 secreted from the xenografted orthotopic CRC model recruits CCR1+ MDSCs and leads to aggressive tumour growth." (PMID 40852716, 2025). "Moreover, CCR1+CD14+ monocytes present in tumor lesions express PD-L1, B7-H3 and TIM-3, and enhance angiogenesis and metastasis." (PMID 40136652, 2025). "To investigate whether ZBP1 modulates CCR1 expression in tumor cells via CCL7 produced by CAFs, we employed a co-culture system." (PMID 41430036, 2025). "Importantly, CCR1 knockdown reversed the tumor-promoting effects of CCL15, providing strong evidence that CCL15 exerts its oncogenic role in ESCC primarily through CCR1 activation." (PMID 40740234, 2025). "Additionally, the regulatory mechanisms of CCR1 and its ligands in immune cells are believed to function similarly in MM cells, indicating that CCR1 contributes to physiological and pathological processes within the tumor microenvironment (TME)." (PMID 40597436, 2025). "Notably, Ccr1 is expressed by newly recruited monocytes, macrophages, and granulocytes in our model, suggesting a potential mechanism for tumor infiltration and invasion." (PMID 41384492, 2025). "We used Ccr1- and Ccr2-deficient mice and two different tumor cells lines, MC38 and LLC1 with and without Ccl2-deficiency in vitro and in vivo." (PMID 39566333, 2025). "Furthermore, subcutaneous xenograft assays in nude mice demonstrated that CCR1 promotes tumor growth in vivo." (PMID 40740234, 2025). "Notably, most studies to date have focused on the paracrine function of CCL15—namely, its role in recruiting CCR1+ immune cells to the tumor microenvironment." (PMID 40740234, 2025). "Of note, both tumor cell lines produce minimal levels of Ccr1-specific chemokines." (PMID 39566333, 2025). "Furthermore, treatment with a neutralizing anti-CCR1 mAb to mice reconstituted with Cxcr2−/− BM significantly suppressed tumor growth and liver metastasis." (PMID 38750114, 2024). "By analyzing the relationship between expression levels and tumor mutation frequency, we discovered that patients with high CCR1 expression were more likely to be classified as non-proliferative HCC." (PMID 38552222, 2024).
tumor (continued). "CCL9/CCR1 signaling is important for macrophage recruitment, angiogenesis, and tumor cell invasion." (PMID 38291436, 2024). "Furthermore, monocyte recruiting chemokine Ccl5 from Mac1 potentially interacts with Ccr1 in Control tumor monocytes." (PMID 39272209, 2024). "In response to the combination therapy, we find that tumor cells increase production of CCL9, which is associated with greater mobilization of G-MDSCs out of the bone marrow and into the tumor bed, which could be limited by CCR1 inhibition." (PMID 37988164, 2024). "We hypothesize that the anti-cancer effect of CCL9 observed in our in vivo research was a result of mostly anti-cancer leukocyte infiltration of the tumor or a thus far unknown CCL9-mediated mechanism preventing tumor progression beyond CCR1 signaling." (PMID 37185750, 2023). "The reciprocal expression of CCL5 predominantly in ASCs and CCR1 largely in the tumor cells may indicate a specific chemokine receptor interaction in the 3D co-spheroids." (PMID 37444610, 2023). "The Mon Fn1 cell population is characterized by inflammatory features, including increased expression of the chemokine receptors Ccr2 and Ccr1 facilitating cell recruitment, immune suppression and tumor-promoting factors such as galectins (Lgals3/9), and the NLRP3 inflammasome inhibitor Tmem176b." (PMID 37756565, 2023). "Furthermore, the impact of direct contacts between ASCs and tumor cells and the involvement of CCR1 in promoting tumor cell migration were demonstrated." (PMID 37444610, 2023). "Assessing other immune cells in the lungs, we detected a significant increase in the accumulation of T-cells, neutrophils and NK cells after CCR1 inhibition at d21 compared with the respective controls, indicating a shift towards a pro-inflammatory tumour microenvironment in this group." (PMID 36241867, 2022). "BM cells incubated with 4T1-TCM grouped with tumor-infiltrating myeloid cells, BM cells cultured in RPMI media clustered with splenic CD11b+ cells, and BM cells cultured with TCM and CCR1 and CCR5 antagonists associated with CD11b+ cells from the BM of naïve mice." (PMID 35064009, 2022). "We further investigated the expression of key DEeRNAs between tumor and normal samples among different cancer types and identified that the expression level of CCR1, CD3D, PHLDA1, and RASD1 was significantly up-regulated in tumor tissue, as compared with normal tissue." (PMID 36092920, 2022). "Moreover, recruitment of CCR1-expressing myeloid cells promotes tumor invasion and metastasis in colorectal cancer." (PMID 36532057, 2022). "These conflicting reports may be due to differences between pulmonary and bone marrow metastatic microenvironments, or tumor cell-intrinsic factors, such as differences in CCR1 expression." (PMID 35756626, 2022). "Furthermore, signaling of CCL9 through CCR1+ (C-C Motif Chemokine Receptor 1) results in the recruitment of myeloid progenitor cells that facilitate tumor cell invasion." (PMID 36497411, 2022). "In addition, neutrophils can be recruited at the tumor site by CC chemokines acting on CCR1, CCR2, and CCR5, but their targeting must be carefully considered because these chemokines can promote neutrophil antitumor activity." (PMID 35158948, 2022). "An in vitro evaluation of a clinical trial for oncolytic virotherapy with 12 patients revealed that receptor/ligand pairs C-X-C motif chemokine receptor-1 (CXCR1)/IL-8 and CC chemokine receptor 1/CC chemokine ligand 5 (CCR1/CCL5) were involved in successful migration of MSCs to the tumor." (PMID 33287630, 2021). "Interestingly, TGF-β, which is secreted by tumor cells and tumor-infiltrating regulatory T cells, enhances the expression of chemokine receptors CCR1, CCR3, CCR5, CCR6, and CXCR4 on DCs, thereby driving DC migration to the TME." (PMID 34290401, 2021).
tumor (continued). "Targeting CCR1 in cancer patients to reduce metastasis or induce changes in the tumor microenvironment might lead to anti-tumor immune responses due to reduction of monocytic infiltration." (PMID 32963283, 2020). "CCL15 also acts on non-cancer cells in the tumor, for example causing angiogenesis mediated by CCR1 and CCR3 on vascular endothelial cells." (PMID 33182504, 2020). "Increased benefit in terms of tumor inhibition was also obtained by measures that down-regulated CCR1 or CCL5 activities, combined with ICBs directed to PD-1 or PD-L1; here again, major roles were revealed for TAMs and MDSCs as targets whose inhibition potentiates the activities of ICBs." (PMID 32582148, 2020). "Because tumour development is largely orchestrated by inflammation, MSCs exhibit upregulation of various chemokine receptors (CCR1, CXCR5 and CCR2) and adhesion molecules (ALCAM, P-selectin and integrins) to facilitate extensive tropism towards specific tumour sites." (PMID 31908585, 2019). "However, the detailed mechanism of CCR1 upregulation in metastatic tumor cells is poorly understood." (PMID 29212252, 2017). "Previous studies have demonstrated that CCR1 is involved in tumor metastasis in several cancers." (PMID 29212252, 2017). "Here, we show that EGF up-regulates CCR1 expression, suggesting that CCR1 may contribute to EGFR-mediated tumor invasion and metastasis." (PMID 29212252, 2017). "Additionally, CCR1 is an important T cell immunity-mediating factor that regulates the immune response and tumor metastasis." (PMID 28355233, 2017). "Therefore, to determine the relative contribution of BM CCL5 receptor expression to tumor growth and neovascularization, BM from CCR1 or CCR5 null mice was transplanted into WT animals." (PMID 27863423, 2016). "Importantly, cancer cells in human primary tumor tissues that were CCR1, CCR3 or CCR5-positive expressed high levels of vimentin." (PMID 25788271, 2015). "Using ex vivo studies, we have shown that IMCs have pro-tumourigenic properties by promoting the growth and EMT of AT2 cells in culture (Fig3) and abrogation of IMCs by the CCR1 inhibitor provides clear evidence for the pro-tumourigenic/tumour-supportive functions of IMCs (Fig4)." (PMID 26183450, 2015). "Because there are fewer chemokine receptors than chemokine ligands, we first assessed the levels of expression of mRNAs encoding all 18 types of chemokine receptors (CXCR1-6, CCR1-10, XCR1, and CX3CR1) in the inflammatory cells located around the tumor in our patient." (PMID 25123545, 2014). "Thus, expression of CCR1 by cancer cells plays a critical role in enabling fibroblasts to exert tumor supportive function, through increased tumor cell proliferation and potentially indirectly through recruitment of leukocytes." (PMID 24068959, 2013). "However, in the context of co-injection with fibroblasts, silencing of cancer cell CCR1 resulted in a 3-fold reduction in tumor size, almost eliminating the effect of the fibroblasts." (PMID 24068959, 2013). "Above median expression of CXCR2, CXCR3 and CCR1 in the tumour islets is associated with increased survival in NSCLC, and expression of CXCR3 correlates with increased macrophage and mast cell infiltration in the tumour islets." (PMID 20429924, 2010). "CCR1 expression was found on infiltrating mononuclear and polynuclear giant cells in the tumor." (PMID 18215331, 2008). "However, it remains unclear whether CCL15 secreted by tumor cells can also act directly on CCR1 expressed on the same tumor cells to exert tumor-regulatory effects." (PMID 40740234, 2025). "Notably, CCR1 knockdown reversed the tumor-promoting effects of rhCCL15 on ESCC cells." (PMID 40740234, 2025). "Notably, CCR1 knockdown reversed the tumor-promoting effect of rhCCL15." (PMID 40740234, 2025). "However, less attention has been paid to the tumor-intrinsic role of CCR1." (PMID 40740234, 2025).
tumor (continued). "However, whether CCL15 can directly activate CCR1 expressed by tumor cells themselves to drive tumor progression remains unclear." (PMID 40740234, 2025). "Although we previously demonstrated that disruption of CCR1-mediated myeloid cell accumulation suppressed tumor progression in syngeneic mouse models, it remains unclear whether disruption of CXCR2-mediated myeloid cell accumulation can suppress tumor progression." (PMID 38750114, 2024). "To understand the cause of CCL5-mediated reduced survival in PDAC, we hypothesized that immune cells responsive to a CCL5 chemotactic gradient (through expression of the cognate receptors CCR5, CCR3, or CCR1) could be potential contributors to an adverse tumor immune environment." (PMID 39656086, 2024). "In the transplanted tumor model, mice reconstituted with Ccr1−/−Cxcr2−/− BM (Ccr1−/−Cxcr2−/− > WT mice) exhibited dramatically smaller tumors compared with recipients of wild-type BM (WT > WT mice), Ccr1−/− BM (Ccr1−/− > WT mice) and Cxcr2−/− BM (Cxcr2−/− > WT mice)." (PMID 38750114, 2024). "Above all, CCL18/CCL3 blockade could elicit significant antitumor effects in ESCC through preventing the infiltration of tumor-associated macrophages and proliferation of ESCC cancer cells, which might be mediated by CCL3/CCR1, CCL3/CCR5 and CCL18/PITPNM3 pathways." (PMID 36850011, 2023). "Notably, their discovery of the interactive secretome between tumour cells and AM-like TAMs in this model, through cholesterol-regulating Niemann–Pick C2 protein and CC chemokine receptor 1 (CCR1) ligands, directed their current study investigating pro- and anti-tumourigenic effects of statins." (PMID 37144683, 2023). "Furthermore, several CCR1 antagonists have been shown to reduce MM tumor burden in animal models." (PMID 35399952, 2022). "Furthermore, there was increased differentiation of inflammatory fibroblasts, accelerated tumor progression, and enhanced C-C chemokine receptor type 1 (CCR1)-mediated MDSC infiltration when Tregs were depleted in a PDAC mouse model, suggesting that Tregs inhibit tumorigenesis in PDAC." (PMID 36077772, 2022). "Thus, we hypothesized that STAT3 contributes to tumor invasion and metastasis by regulating CCR1 expression." (PMID 29212252, 2017). "In contrast, downregulation of CC inflammatory chemokine receptors, namely CCR5, CCR2, and CCR1, was a common feature of primary Mn and Mn-derived Mf response to low pO2 and an important mechanism regulating their retainment/concentration in hypoxic areas of inflammatory and tumor lesions." (PMID 28936211, 2017). "BL6, Ccr1-/- and Ccr2-/- mice were subcutaneously injected with LLC1.1 wt cells, the primary tumor was removed on day 14 and BL6 and Ccr2-/- mice were i.v. injected with fluorescently labeled Ccr2-/- enriched CD115+ monocytic cells." (PMID 39566333, 2025). "ZBP1 deficiency reduces CCL7 expression in CAFs, diminishing their ability to promote tumor cell proliferation, migration, and invasion via the CCL7/CCR1 axis." (PMID 41430036, 2025). "Taken together, these data demonstrated that ZBP1 enhanced tumor cell invasiveness and metastatic potential by regulating CAF-secreted CCL7 to activate CCR1-dependent signaling pathways." (PMID 41430036, 2025). "Reduced metastasis with both MC38-Ccl2KD and LLC1.1-Ccl2KD tumor cells correlated with a reduction in macrophages (F4/80+ cells) and myeloid cells in the metastatic lesions of BL6 as well as Ccr1-/- mice." (PMID 39566333, 2025). "One, three and five days after the removal of the primary tumor, ATs with CD115+ cells from both BL6 and Ccr2-/- mice restored metastasis in Ccr1-/- mice to the same levels as observed in BL6 mice." (PMID 39566333, 2025). "In contrast, CCR1 and CCR5 were decreased in tumor-infiltrating NK cells, which promote NK liver homing." (PMID 40315330, 2025).